CCR3 (C-C motif chemokine receptor 3)
Diseases named in the same sentence as CCR3 in open-access papers (continued):
Sharing a sentence is not in itself a finding about the gene and the disease.
infectious colitis (1 paper, 2024). A viral or bacterial infectious process affecting the large intestine. "The reciprocal regulation of CXCR2 and CCR3/CCR10 in neutrophils and each receptor’s contribution to neutrophil migration and retention during infectious colitis requires further study." (PMID 39193987, 2024).
interstitial lung disease (1 paper, 2020). A diverse group of lung diseases that affect the lung parenchyma. "A recent study suggests that the unique N-terminal extension domain of human NRS (UNE-N) interacts with CCR3, mediating proinflammatory signaling in interstitial lung disease." (PMID 32117966, 2020).
ischemia (1 paper, 2016). A hypoperfusion of the BLOOD through an organ or tissue caused by a PATHOLOGIC CONSTRICTION or obstruction of its BLOOD VESSELS, or an absence of BLOOD CIRCULATION. "The finding that knockdown or knockout out of CCR3 led to protection against OGD or transient focal ischemia helps to support the concept that CCR3 contributes to ischemic injury." (PMID 27822494, 2016). "These initial findings support the need for additional investigations into the actions of CCR3 in neuronal demise to determine whether inhibiting CCR3 could provide a new avenue for the future treatment of ischemia injury or neurodegenerative disease." (PMID 27822494, 2016). "First, the role of CCR3 in ischemic injury could be completely independent of its initiation downstream of DNA damage, since the paradigm inhibits CCR3 upstream of DNA damage, and thus decouples the MNNG experiments from the ischemia models." (PMID 27822494, 2016).
ischemic stroke (1 paper, 2024). A stroke disorder caused by obstruction of blood flow to the brain, due to thrombotic (local blood clot formation) or embolic (due to a blood clot or other material traveling from another site) event. "Further investigation is needed to examine the relationship between CCR3 and infarct and edema volumes after ischemic stroke in both animal models and human patients." (PMID 38332938, 2024). "We measured the change in expression of CCR3 and its ligands (CCL5, CCL11, and CCL24) in the venous blood prior to and after occlusion in our transient rat model of ischemic stroke." (PMID 38332938, 2024). "We found that the change in gene expression of CCR3 and ligands (CCL5, CCL11, and CCL24) is positively correlated with infarct volume in our transient rat model of ischemic stroke." (PMID 38332938, 2024).
joint inflammation (1 paper, 2025). "Experimental models have shown that the pharmacological inhibition of CCR3 can attenuate leukocyte infiltration and joint inflammation, and similar findings have been reported in eosinophilic inflammation." (PMID 40507021, 2025).
liver fibrosis (1 paper, 2026). "Our findings reveal that Tet2−/− pMDMs are a major source of elevated Ccl2 and Ccl8 in Tet2ΔMye-CCl4 mice, and Tet2−/− monocytes showed an increased expression of Ccr2 and Ccr3, which, thus, created a positive feedback loop that amplifies MDMs infiltration and liver fibrosis." (PMID 41474968, 2026).
lymph node metastasis (1 paper, 2021). "In the CCR1-negative/CCR3-positive/CCR5-negative group, CCL5 immunoreactivity was significantly correlated with the pT, histological grade, Ki67 LI and MVD and tended to be correlated with lymph node metastasis while negatively correlated with the ER and PR." (PMID 33671956, 2021).
mastitis (1 paper, 2025). Inflammation of breast tissue during lactation or postpartum due to an obstructed duct or infection. "DEGS such as IL10, CCL5, IL1B, OSM, TNFRSF1B, IL7, and CCR3, among others, implicated in these pathways, may play a crucial role in the development of subclinical mastitis in Bactrian camels, though further analysis is needed to explore their potential functions." (PMID 40005880, 2025).
mastocytosis (1 paper, 2018). A clonal myeloproliferative neoplasm characterized by the proliferation and accumulation of neoplastic mast cells in one or multiple organs or organ systems. "Thus, we carefully selected complementary systems (ΔdblGATA deficiency, CCR3 deficiency and CCR3 depleting antibody) to selectively target eosinophils whilst controlling for potential ‘off-target’ impact on basophilia or mastocytosis during peritoneal Brugia malayi larval infection." (PMID 29547639, 2018).
metabolic dysfunction-associated steatohepatitis (1 paper, 2025). Metabolic dysfunction-associated steatohepatitis (MASH, formerly known as nonalcoholic steatohepatitis or NASH) is a type of fatty liver disease. "Higher levels of CCL24 and CCR3 were found in the tissue and sera of patients with fibro-inflammatory diseases, including primary sclerosing cholangitis (PSC), systemic sclerosis (SSc), and metabolic dysfunction-associated steatohepatitis (MASH)." (PMID 39851534, 2025).
mouth ulcers (1 paper, 2019). "In the 3p21 locus, rs4683205 near CCR3 showed strong evidence for a moderate effect on mouth ulcers (OR 1.10, 95% CI: 1.09, 1.11; EAF 0.47; P = 4.9e−106)." (PMID 30837455, 2019). "Additional variants in this region (e.g. rs4493469 near CCR3 and rs34390431 near CCRL2) also showed strong evidence for an association with mouth ulcers after clumping." (PMID 30837455, 2019).
Myocardial fibrosis (1 paper, 2020). "CCL11 bind CCR3 to stimulates the migration of immune cells like neutrophils and was shown to recruit such cells to the heart and contribute to myocardial fibrosis." (PMID 32923679, 2020).
myocardial ischemia (1 paper, 2015). A disorder of cardiac function caused by insufficient blood flow to the muscle tissue of the heart. "In this study, we have dissected CCR3’s role in healing after MI, using a pharmacological CCR3-antagonist in a mouse model of myocardial ischemia/reperfusion." (PMID 32309568, 2015). "In the present study, the role of CCR3 in myocardial ischemia/reperfusion was established.METHODS AND RESULTS: One week after infarct induction in a mouse coronary ligation model, the functional and morphological parameters of the heart were analyzed." (PMID 32309568, 2015).
myocarditis (1 paper, 2010). Myocarditis is a condition that is characterized by inflammation of the heart muscle (myocardium). "Accordingly, we found decreased expression of CCR3 (a Th2-associated receptor) and increased expression of CCR5, a receptor crucial for the development of myocarditis." (PMID 20169058, 2010).
nephritis (1 paper, 2023). Inflammation of renal tissue. "In individuals with immunological thrombocytopenia, the expression of the Th1- and Th2-associated chemokine CCR3 gene was reduced, and animals lacking the chemokine receptor CCR1 had elevated Th1 responses and glomerular damage in nephritis." (PMID 36976996, 2023).
oral carcinoma (1 paper, 2015). "Similarly, a CCL7 neutralizing antibody has been shown to inhibit CCL7-induced invasion and migration of oral carcinoma cells, and anti-CCL2 and-CCR3 antibodies are also being evaluated." (PMID 26046767, 2015).
osteoarthritis (1 paper, 2017). A noninflammatory degenerative joint disease occurring chiefly in older persons, characterized by degeneration of the articular cartilage, hypertrophy of bone at the margins and changes in the synovial membrane. "Interestingly, an upregulated expression of CCR3 receptor has been found in osteoarthritis cartilage and on human chondrocytes indicating that CCR3 play a role in inflammatory cartilage destruction." (PMID 28706221, 2017).
peripheral nerve injury (1 paper, 2022). Injury to a peripheral nerve. "Our research is the first comprehensive behavioral and biochemical study showing that many endogenous ligands of CCR1 (CCL2/3/5/7/8/9) and CCR3 (CCL5/7/8) are significant in the development (CCL2/3/5/7/8/9) and maintenance (CCL2/7/8) of neuropathic pain after peripheral nerve injury in mice." (PMID 36611891, 2022).
pleural tumor (1 paper, 2024). "Using the SB297006 to knockdown CCR3 in MPE models, we observed impaired eosinophil recruitment, increased pleural tumor burden, and MPE volume." (PMID 38951159, 2024).
presbycusis (1 paper, 2018). Bilateral hearing loss caused by progressive degeneration of cochlear structures and central auditory pathways, typically associated with the aging process. "Yang Dong and his team found that CCR3 and GILZ genes played an important role in the pathogenesis of presbycusis, probably by regulating chemokine receptors, T-cell apoptosis, or T-cell activation pathways." (PMID 29392088, 2018). "So, the CCR3 and GILZ genes can also be used as a potential biomarker for Presbycusis." (PMID 29392088, 2018).
prostate tumors (1 paper, 2024). "Compared to primary prostate tumors, CCR3 exhibits high expression in bone and visceral metastases, potentially exerting its effects via the CCR3/CCL7 axis." (PMID 38511143, 2024).
rectal cancer (1 paper, 2021). A primary or metastatic malignant neoplasm that affects the rectum. "For rectal cancer, statistical significance was demonstrated for CEA, CRP, and CCR3 (p = 0.003; p < 0.001; p = 0.012, respectively)." (PMID 34204490, 2021).
retinal pigmentosa (1 paper, 2017). "The suppression of both CCR3 and CCR1 signaling may have the stronger potential than the suppression of selective CCR3 signaling against the photoreceptor degeneration which is observed in dry AMD and retinal pigmentosa." (PMID 28458639, 2017).
Salmonella Infections (1 paper, 2024). Infections with bacteria of the genus SALMONELLA. "CCL28 stimulation of bone marrow neutrophils in vitro increased their antimicrobial activity and ROS production during Salmonella infection, which was reverted by blocking CCR3 but not CCR10." (PMID 39193987, 2024).
sarcoma (1 paper, 2022). A usually aggressive malignant neoplasm of the soft tissue or bone. "Gene expression analysis showed five genes (homeobox A10 (HOXA10), GATA binding protein 3 (GATA3), prostaglandin D2 receptor 2 (PTGDR2), thymocyte selection associated high mobility group box (TOX), and C-C motif chemokine receptor 3 (CCR3)) were dysregulated (p < 0.05) in sarcoma patients." (PMID 36005179, 2022). "There is a need for more extensive studies on these genes, as the PTGRD2, CCR3, TOX, and HOXA10 genes are still underexplored in sarcomas." (PMID 36005179, 2022). "Overall, sarcoma studies related to PTGDR2, CCR3, and HOXA10 are still lacking." (PMID 36005179, 2022).
SARS-CoV infection (1 paper, 2009). "It is important to note that at 3 h post infection, the CCR-3 expression in mock infected adult DCs was very low (average <1 copies per 104 β-actin) but it increased to 183.91 ± 128.35 copies per 104 β-actin after SARS-CoV infection." (PMID 19505311, 2009).
ZIKV infection (1 paper, 2021). "Our data demonstrate that neutralizing antibodies and small-molecule CCR3/CCR5 receptor antagonists inhibit persistent ZIKV infection of hBMECs and as a result have the potential to prevent ZIKV spread to neuronal compartments and across placental barriers." (PMID 34399621, 2021). "Following ZIKV infection, CCR3 or CCR5 antagonists also dramatically reduced the number of ZIKV-infected hBMECs and expressed NS5 and Env proteins." (PMID 34399621, 2021). "Daily CCL5 neutralization decreased the number of ZIKV-infected hBMECs by only 20%, while neutralizing antibodies to CCR3/CCR5 receptors reduced ZIKV infection by 50% compared to controls." (PMID 34399621, 2021). "Knockout of the CCL5 receptors CCR3 and CCR5 limits ZIKV infection of hBMECs." (PMID 34399621, 2021). "To determine the effects of CCL5 on hBMECs, we first determined whether neutralizing antibodies to CCL5, CCR3, or CCR5 altered ZIKV infection and hBMEC viability." (PMID 34399621, 2021). "Neutralizing antibodies to CCL5, CCR3, or CCR5 inhibited persistent ZIKV infection of hBMECs." (PMID 34399621, 2021).
Zinc deficiency (1 paper, 2019). A deficiency of the essential metal Zinc; an essential cofactor for many enzymes. "Therefore, CXCR2, ANXA1, and CCR3 would be potential biomarkers for zinc deficiency in mice." (PMID 30770772, 2019).
tumor (100 papers, 2007 to 2026). "CCR3 signaling have been implicated in processes like angiogenesis, tumor cell migration, and metastasis." (PMID 40484866, 2025). "As the primary ligand of CCR3 (C‐C Motif Chemokine Receptor 3), Eotaxin‐1 has been identified as involved in the tumor‐associated inflammation that facilitates the development and progression of CCR3‐positive RCC." (PMID 37902279, 2023). "At proximity to CCR3-deficient tumours in obese animals, as expected, adipocytes were hypertrophic compared with those of lean mice, increasing PPAT thickness." (PMID 26756352, 2016). "In addition, CCL24 can combine with CCR3 to recruit eosinophils and tumor-associated macrophages, and immune function is limited when CCR3/CCL24 is suppressed." (PMID 36976996, 2023). "CCL24 did not directly alter CD8+ T cell populations; instead, CCL24+ tumor cells recruited CCR3+ TAMs, which promote immunosuppression by promoting nuclear translocation of YAP1, a key transcription factor of the Hippo pathway." (PMID 41694595, 2026). "The combined use of IL‐1R and CCR3 inhibitors significantly suppressed tumor progression in liver metastasis, liver weight, and the estimated metastasis site, and improved OS." (PMID 40397411, 2025). "Another report showed that interaction of CCL26 and CCR3 regulates the Th2-dominant tumor environment." (PMID 39931245, 2025). "This suggests that the combined therapy impairs tumor cell survival strategies such as DNA damage response, metabolic maintenance, and immune function (including CCR3, SPNS3, SPPL3, and BTN2A2)." (PMID 41404060, 2025). "Studies on RCC have revealed the significant overexpression of the CCL11 receptor CCR3 in tumor cells." (PMID 40429807, 2025). "To demonstrate the on-target effects of anti-CCR3 antibody, we also evaluated the immunogenicity and anti-tumor effect of XCL1-E6E7 with XCR1 as the specific receptor in mice with or without CCR3 + cells." (PMID 38459592, 2024). "CCL8 is a monocyte chemokine that can interact with CCR1, CCR2B, and CCR3; it also regulates tumor occurrence, antiviral infections, and inflammatory immunity in the host." (PMID 39185422, 2024). "In tumor tissues under hypoxic environments, CCR3 expressed in vascular endothelial cells, and CCR10 expressed in Treg cells, both receptors for CCL28, have been reported to contribute to promoting the angiogenesis process through hypoxia-induced CCL28." (PMID 38534417, 2024). "Another study showed that PPAT secretes the chemokine CCL7, which diffuses from PPAT into the peripheral zone of the prostate and stimulates the migration of CCR3-expressing tumor cells." (PMID 38164282, 2024). "Inhibition of CCR3 activity in ATX-depleted tumors led to significant rescue of tumor growth and reduced eosinophil infiltration compared to vehicle-treated, ATX-depleted tumors." (PMID 38195933, 2024). "The role of CCR3 in tumor cells is relatively limited, as it is primarily highly expressed in inflammatory cells such as mast cells, eosinophils, basophils, and Th2 cells." (PMID 38511143, 2024). "CCR3-specific blockade in NFSA tumor-bearing mice increased tumor angiogenesis and blocked eosinophil infiltration, but no significant change in tumor weight was seen." (PMID 37587450, 2023). "CCR3 can induce the chemotaxis of eosinophils in the blood and spleen of tumor-bearing mice to infiltrate into the tumor site and exert anti-tumor activity." (PMID 37005677, 2023). "Consistently, CCR3 was upregulated in WPOI 4–5 tumor cells and showed a marked dysregulated elevation in EMT pathway-related genes in HNSCC patient samples, which correlated with a high incidence of recurrence of various human cancers." (PMID 36045118, 2022). "As before, CCL26 promoted matrix invasion by tumor cells in the OXTRLow CAF/Tumor co-culture model but this was abrogated by CCR3 knockout." (PMID 36045118, 2022). "Confocal microscopy analysis showed the cellular co-localization of CCL11 and CCR3 in HNC tumor cells." (PMID 35804913, 2022).
tumor (continued). "Immunohistochemical staining of CCL11 was observed in the putative area where CAFs and tumor from a representative case delineated the same area, and distribution of CCR3 investigated in the same area showed that both expressions coexisted." (PMID 35804913, 2022). "Proliferation of tumor cells was significantly reduced after 72 h arguing for a direct effect of CCL11 on CCR3 that in turn promotes cell proliferation (*p < 0.05)." (PMID 33608009, 2021). "CCR3 has been reported to promote tumor progression in some kinds of carcinomas, showing agreement with our findings." (PMID 33671956, 2021). "Having demonstrated the role of CCR3 in in vitro directed migration, we evaluated if the bone metastatic sites were enriched with tumor cells expressing this receptor." (PMID 33671469, 2021). "For PCa, the migration towards both surrounding (PPAT) or distant adipose tissue (BM-adipose tissue) is dependent of CCR3 suggesting the predominance of tumor type over depots." (PMID 33671469, 2021). "Almost all tested parameters (CCL11, CCL24, and CCR3) showed higher SE than commonly used tumor marker CA 19-9." (PMID 34204490, 2021). "Both 4T1 tumor cells and neutrophils isolated from lung parenchyma displayed significant CCR3 expression as measured by FACS." (PMID 33608009, 2021). "We indicated that the highest SE from all tested parameters revealed CCR3 (68%) and this value is comparable to SE of C-reactive protein (72%) and higher than SE of commonly used tumor marker CA 19-9 (40%)." (PMID 34204490, 2021). "IL‐5 secretion in tumor microenvironment leads to activation of CCR3 (CC motif chemokine receptor type 3)‐expressing eosinophils in blood and spleen of tumor‐bearing mice." (PMID 34128588, 2021). "Interaction between CCL7 and its ligand CC-chemokine receptor 3 (CCR3) will allow tumor migration outside of prostatic gland and initiate metastatic process." (PMID 34354670, 2021). "SP for CCR3 (62.07%) was comparable to results of both tumor markers (CA 19-9 and CEA) but lower than SP observed for CRP (79.31%)." (PMID 34204490, 2021). "Flow cytometry analysis of tumor, blood, spleen, and bone marrow (BM) samples demonstrated that anti-CCR3 antibody administration depleted most circulating CD45+CD11b+Gr-1loF4/80+Siglec-F+MHC-II- eosinophils." (PMID 33754022, 2021). "CCR3 immunoreactivity was significantly upregulated in tumours from PRADT patients (p = 0.04, Wilcoxon Rank Sum test)." (PMID 28753854, 2018). "The expression of both CCL11 and CCR3 on the tumor cells can lead to homotypic aggregation, which can be observed as cohesive clusters of tumor cells, a characteristic finding in ALCL." (PMID 29915722, 2018). "Note that some blood vessels (indicated by blue stars) also express CCR3 but that quantification was only performed in tumour glands (indicated by arrows) under the supervision of two pathologists." (PMID 26756352, 2016). "Intriguingly, classical M2 markers including Cd206 (Mrc1), Cd163, Pdl2 (Pdcd1lg2), Ccr3, Arg1 and many others were all markedly downregulated in TAMs isolated from the St2−/− background as compared with those isolated from tumours grown in wt mice." (PMID 27150562, 2016). "Based on these observations in vivo, we conclude that CCL7 has a critical role in tumor proliferation and metastasis and this role is related to CCR3." (PMID 27167205, 2016). "Our primary goals were to explore the clinical significance of CCL11/CCR3 in tumor progression, and to find out valuable prognostic and predictive biomarkers in GBM." (PMID 27119233, 2016). "Of note, CCR3 was significantly over-expressed in tumours from obese patients (body mass index (BMI) 30–35 kg m−2, 7.9 % of the cohort)." (PMID 26756352, 2016). "Although we assessed that the short-term (up to 5 days) growth of CCR3-deficient cells was similar to wt cells, we cannot formally exclude that long-term CCR3 depletion intrinsically affects tumour growth and survival." (PMID 26756352, 2016).